GBP1 (guanylate binding protein 1)
Diseases named in the same sentence as GBP1 in open-access papers (continued):
Sharing a sentence is not in itself a finding about the gene and the disease.
tumor (continued). "We then analyzed the mRNA expression profile of GBP1 in a collection of 21 GBM tumor specimens by quantitative RT-PCR (RT-qPCR)." (PMID 26848767, 2016). "Consistent with this, hematoxylin and eosin (H&E) staining of the xenograft tumor tissues showed increased cancer cell density in the GBP1 expressing tumor." (PMID 26848767, 2016). "GBP1 + neutrophils (Neu_4), characterized by response to interferon, exhibited increased innate immune activities and the production of cytokines that activate anti-tumor immunity, significantly correlated with improved survival." (PMID 41689690, 2026). "Inhibiting GBP1 may overcome resistance in cancers such as ovarian and lung, where sh-GBP1 inhibits tumor growth and restores erlotinib sensitivity by disrupting EMT signaling and IDO-1 interactions." (PMID 40564939, 2025). "Additionally, we have found HLA-B as a hub gene across all regions and is negatively correlated with GBP1 in the normal region and positive partial correlation in the tumor region." (PMID 39954675, 2025). "Could their immune roles modulate microbiome-tumor interactions, given LPS recognition’s overlap with gut flora and GBP1’s gastrointestinal expression ?" (PMID 40564939, 2025). "Notably, Guanylate-Binding Protein 1 (GBP1) mRNA levels were significantly higher in PD-L1-positive tumor cells." (PMID 40975978, 2025). "The weight and tumor volume of mice were measured at days 0, 7, 14, 15, 16 and 17, and the results showed that the final tumor volume and weight of mice in the GBP1 overexpression group were significantly increased compared with the negative control group (t1 = 11.10, t2 = 13.26, p < 0.0001)." (PMID 38167153, 2024). "The anti-tumor activity of GBP-1 was first highlighted by the finding that cytokine-induced inhibition of angiogenic growth factor-induced proliferation of cultured human endothelial cells (HUVECs) resulted in the expression of GBP-1." (PMID 39457021, 2024). "Thus, the observed predictive effect of GBP1 raised the question of which cells expressed GBP1, and how they contribute to anti-tumor immunity." (PMID 38758367, 2024). "Pro-inflammatory and immunosuppressive cytokines were significantly elevated in tumors with high GBP1 expression, which suggests that GBP1 could support anti-tumor immunity." (PMID 38758367, 2024). "Moreover, we found that GBP1 had a strong positive correlation with immune score and tumor microenvironment score." (PMID 38167153, 2024). "Interestingly, the KD of GBP-1 in SNB19 GBM cells resulted in significantly less tumor invasion than in cells with control shRNA after an intracranial xenograft." (PMID 39457021, 2024). "GBP1 exhibits anti-tumor effects by inhibiting tumor cell proliferation." (PMID 38753689, 2024). "The role of GBP1 in tumors is complex, and both anti- and pro-tumor effects have been reported." (PMID 38758367, 2024). "GBP1 has been reported to play an important role in tumor immunity." (PMID 38167153, 2024). "The predominant expression of GBP1 in macrophages indicates that it supports their anti-tumor role." (PMID 38758367, 2024). "On the other hand, a large number of studies have shown that the high expression of GBP1 in lung cancer could promote the invasion and metastasis of tumor cells, and have certain drug resistance." (PMID 38167153, 2024). "However, the expression of genes participating in AP (e.g., HLA‐DRA/DMB and CD74) and anti‐tumour immunity (e.g., GBP1, IFNG and TNFRSF9) were significantly higher in the TS, while genes involved in angiogenesis (e.g., VEGFA) was significantly higher in TN." (PMID 37491740, 2023). "In addition, high expression of GBP1 was detected in tumor tissues using immunohistochemical staining." (PMID 37796192, 2023). "However, a systematic analysis of GBP1 impacting clinical efficacy and tumor immune microenvironment changes in pan-cancer patients is still scarce." (PMID 35222540, 2022).
tumor (continued). "Overall, patients with high GBP1 expression might show low tumor immune dysfunction and exclusion and high immunogenicity, resulting in better responses to immunotherapy." (PMID 35222540, 2022). "GBP-1 also inhibits tumor cell growth by inhibiting angiogenesis." (PMID 35681772, 2022). "Since the effects of GBP1 across different cancers remain elusive and the potential role of GBP1 in anti-tumor immune response has been represented in the previous studies, a comprehensive pan-cancer analysis is urgently needed to explore the possibility of GBP1 being a biomarker for immunotherapy." (PMID 35222540, 2022). "As such, a further question is, if GBP-1 is a direct contributor, whether this activity cell is autonomous within the tumor cells themselves or the consequence of the infiltrating activated T-, B-, and NK cells, or a combination of both." (PMID 35681772, 2022). "However, how GBP 1, 2, 3, 4 participate in the regulation of tumor immune-infiltrating cells requires further research to clarify." (PMID 34759950, 2021). "Furthermore, the correlation analysis of immune infiltration showed that the expressions of GBP1, 2, 3, 4 were significantly and positively correlated with the level of tumor immune-infiltrating cells." (PMID 34759950, 2021). "GBP-1 is expressed in both tumor and non-tumor cells in these tumors." (PMID 34830789, 2021). "GBP-1 also has properties that would suggest it could improve prognosis in a tumor cell-autonomous manner." (PMID 34830789, 2021). "In addition, the potential role of soluble GBP1 as a biomarker of a Th1/CTL response in the EOC tumor environment should be considered." (PMID 32093058, 2020). "Since GBP1 expression mediates anti-tumor effects in different models, we asked whether GBP1 had inhibitory effects in EOC cell models in vitro." (PMID 32093058, 2020). "The expression and activity of GBP1 are closely related to the tumor microenvironment." (PMID 33552086, 2020). "Since GBP1 has been involved in tumor biology, here we focused on this protein." (PMID 32093058, 2020). "Our data show for the first time that cytokine-stimulated tumor cells release soluble GBP1 in vitro and in vivo and suggest that GBP1 may have anti-tumor effects in EOC." (PMID 32093058, 2020). "Moreover, full-length GBP1 accumulates in patients’ ascites, suggestive of a potential role in the tumor microenvironment." (PMID 32093058, 2020). "However, how GBP1 is secreted out of cells in the body and its relationship with tumor microenvironment and inflammation warrant further verification." (PMID 33552086, 2020). "In addition, Astragaloside IV reduces the extracellular secretion of IDO1 by blocking the interaction of IDO1 and GBP1, thereby reducing T cell exhaustion and inhibiting tumor progression." (PMID 33552086, 2020). "In vivo study revealed that knock-down of IDO1 and GBP1 inhibited tumor growth and metastasis." (PMID 33552086, 2020). "The degree to which this is true in the complex setting of the tumor microenvironment is, at present, unknown and further studies are needed to delineate the lineage-specific activity of GBP1 in the tumorigenic process." (PMID 32117203, 2019). "Therefore, carefully dissecting the patterns of GBP1 expression in large series of clinical tumor samples will help to identify its role in cancer and provide us clue for further targeting strategies." (PMID 31998647, 2019). "Correlations between tumor GBP1 expression and clinical variables." (PMID 31998647, 2019). "Similarly, significantly reduced tumor weight in the GBP1 gene KO xenografts in both groups was verified in comparison to their control tumors." (PMID 31998647, 2019). "However, when GBP1-overexpressing cells (U87-GBP1) and control cells (U87-LacZ) were subcutaneously implanted into the flank of nude mice, we found that forced expression of GBP1 dramatically increased tumor growth rate compared to the vector control group." (PMID 26848767, 2016).
tumor (continued). "Furthermore, GBP-1 impedes the growth of tumor cells by restraining angiogenesis." (PMID 38460960, 2024). "In addition, we found that GBP1 had a strong positive correlation with immune score and tumor microenvironment score, indicating that GBP1 expression is significantly correlated with tumor microenvironment, and plays an important role in the occurrence and development of tumors." (PMID 38167153, 2024). "In addition, some studies have shown that tumor cells expressing GBP1 can promote tumor growth." (PMID 38758367, 2024). "Nevertheless, GBP1 expression may correlate with aggressive behavior in other cancers, including esophageal carcinoma or glioblastoma, or with radio- or chemo-resistant phenotypes in different tumor cell types, including ovarian and head and neck carcinoma." (PMID 32093058, 2020). "It is now known that GBP1 expression is not only virus/cytokine inducible, but chemotherapy-created stress is also inducible for its expression, indicating a possible complex GBP1 expression in a given tumor where areas of tumor cells may exist in significantly different microenvironment niches." (PMID 31998647, 2019). "Importantly, silencing of GBP1 using RNA interference markedly inhibited EGFRvIII-mediated GBM tumor growth in mice, suggesting that GBP1 might serve as a potential therapeutic target for treatment of the large percentage of GBMs with the EGFRvIII mutation." (PMID 26848767, 2016). "GBP1 codes for the Guanylate-Binding Protein 1 (GBP1), binding activated T lymphocytes and enabling tumor cells to cross the BBB." (PMID 40076927, 2025). "These core genes contained at least 8 (PPP2R2A, CXCL10, CXCL11, GBP1, IRF1, RARRES3, STAT1, and TAP1) previously identified regulators of tumor progression and distant metastasis." (PMID 38545852, 2024). "In tumour xenografts, the expression of multiple characteristic SASP factors, including GATA4, MMP2/10, ITGA2 and GBP1, significantly increased after PRC2 inhibition, contributing to ECM remodelling and tumour regression." (PMID 39270064, 2024). "The expression of GBP1 and GBP1P1 was significantly higher in the tumor compared to the normal tissue." (PMID 38072995, 2023). "The expression levels of GBP1 and its pseudogene, GBP1P1, were significantly upregulated in tumor samples." (PMID 38072995, 2023). "Results of tissue microarray IHC further certificated GBP1, BIN2 and LAP3 were overexpressed in EBVaGC tumour tissues." (PMID 36519208, 2023). "As expected, the expression of GBP1 and its pseudogene GBP1P1 were significantly higher in tumor samples." (PMID 38072995, 2023). "Using IHC to stain for GBP1 expression, a FFPE tissue sample from the original PSaRC318 tumor did indeed demonstrate diffuse cytoplasmic staining for GBP1 (left)." (PMID 36187937, 2022). "While treatment of GBM cells with either EGF or IFN-γ induces the expression of GBP-1, only EGF treatment induces the expression of matrix metalloproteinase 1 (MMP1) and promotes tumor cell migration/invasion." (PMID 35681772, 2022). "The subsequent analysis further demonstrated that patients with high GBP1 expression had hot anti-tumor immune phenotypes (HIC), low tumor immune dysfunction and exclusion (low TIDE scores), and high immunogenicity (high IPS)." (PMID 35222540, 2022). "The results showed that the expressions of GBP1 and GBP2 in normal tissues were significantly higher than those in tumor tissues." (PMID 36246628, 2022). "Patients with high GBP1 expression were more likely to belong to HIC and displayed “hot” anti-tumor immune phenotypes." (PMID 35222540, 2022). "We continued to explore the prognostic value of GBP1, 2, 3, 4 in LGG patients using GEPIA database by evaluating the effect of gene expression on overall survival and disease-free survival of tumor patients." (PMID 34759950, 2021). "As shown in the boxplot, IL1B, MST1, GBP1, and NLRP3 were downregulated, and the other 35 PRGs were upregulated in tumor tissues." (PMID 34869364, 2021).
tumor (continued). "Considering that the existing studies have proved the anti-tumor effect of astragaloside IV, we selected astragaloside IV as a candidate interface inhibitor for IDO1 and GBP1." (PMID 33552086, 2020). "Here, we show for the first time that tumor cells, such as the EOC cell lines SKOV3 and OVCAR5 and the primary cells A161, can express and release GBP1, but only after IL-27 or IFN-γ stimulation." (PMID 32093058, 2020). "Then tumor volume was measured, and the tumor tissue was formalin fixed and used for immunohistochemical staining to detect the protein expression of IDO1 and GBP1." (PMID 33552086, 2020). "Guanylate-binding protein 1 (GBP1) is prominent among the involved proteins and its expression appears to be upregulated in the primary tumor specimens." (PMID 29350274, 2018). "Therefore, GBP1 and GBP2 may be also tumor suppressor genes and associated with better prognosis." (PMID 27806724, 2016). "Disrupting GBP1-IDO-1 interactions with agents like astragaloside IV diminishes immune evasion, enhancing chemo- or immunotherapy efficacy, a mechanism evaluable through immune profiling, tumor growth assays, or patient-derived xenografts." (PMID 40564939, 2025). "Specifically, tumor cells educated TANs to overexpress SPP1, GBP1, and ELOVL5, which subsequently activated three key mechanisms: promoting angiogenesis (SPP1-NF-κB-HIF/VEGF), immunosuppression (GBP1-NF-κB-PD-L1), and dysregulated oxidative lipid metabolism (ELOVL5-NF-κB), leading to poor prognosis." (PMID 41313078, 2025). "As GBP1 can be induced by IFN signaling, patients with high GBP1 expression may reflect active IFN signaling, which may represent the active anti-tumor immunity." (PMID 38758367, 2024). "GBP1, as an important member of the GBP family, has the functions of resisting various viruses, bacterias and protozoas, anti-angiogenesis effect, and even anti-tumor effect in some cancers." (PMID 38167153, 2024). "Additionally, high GBP1‐5 expression was related to a better AJCC stage, lower pathology grade, and smaller tumor size." (PMID 37551111, 2023). "When the relative expression of the GBP1/hsa-miR-30d-5p/GBP1P1 axis were compared to patient’s pathological data, the expression of these genes was significantly correlated to lymph nodes metastasis, cancer stage and tumor grade." (PMID 38072995, 2023). "The expression of GBP1 and GBP1P1 in tumor tissue was 3.4-fold and 5.7-fold higher, respectively." (PMID 38072995, 2023). "In contrast, the expression of GBP1 or GBP2 had minor effect on GBM cell growth in vitro but dramatically induced tumor growth in vivo, indicating these GBPs may modulate tumor microenvironment." (PMID 33608513, 2021). "GBP1 is a Guanylate-Binding Protein, which has GTPase activity and has been involved in IFN-mediated anti-microbial, anti-angiogenic, and anti-tumor activities." (PMID 32093058, 2020). "Cellular verification demonstrated that GBP1 and ETV7 may act as tumor suppressors in HGSOC, whereas CXCL13 may promote cell proliferation and migration." (PMID 32544083, 2020). "As it is discovered in our study that the GBP1 protein expresses variably in non-tumor cells like fibroblasts and lymphocytes, and the RNA level GBP1 expression in non-tumor cells exists obviously." (PMID 31998647, 2019). "GBP-1 is one of the most significantly induced proteins in cells exposed to IFN and is involved in its antibacterial, antiviral, anti-angiogenic and anti-tumor activities." (PMID 27683036, 2016). "Based on the networks, we find several hub genes shared across spatial regions, e.g., HLA-B (weighted connectivity degrees: 0.94 for tumor; 0.23 for intermediate; 1.35 for normal), which shows negative partial correlation with GBP-1 in the normal region and positive in the tumor region." (PMID 39954675, 2025). "Indeed, tumor-cells enriched from the ascites of EOC patients displayed constitutively tyrosine-phosphorylated forms of STAT1 and STAT3, and also constitutive GBP1 expression." (PMID 32093058, 2020).
tumor (continued). "A previous report showed that GBP1 could be secreted by endothelial cells but not by the tumor cell lines HeLa and HaCaT." (PMID 32093058, 2020). "Furthermore, the tumor areas with and without the expression of GBP1 were morphologically indistinguishable, except for the presence of TILs in the former." (PMID 29350274, 2018). "In particular, GBP-1 is one of the most IL-27 up-regulated proteins and is also an important mediator of the IFN-γ-mediated inhibition of endothelial and epithelial tumor cell proliferation, migration, and invasion, which results in anti-angiogenic and anti-tumor effects." (PMID 27683036, 2016). "Ipilimumab may also rescue tumor-impaired IFN-γ pathways in CD4+ T cells, since a number of genes associated with IFN-γ signals such as STAT1, ISG15, GBp1, and EIF2AK2 were up-regulated by ipilimumab (data not shown)." (PMID 22788688, 2012). "However, the role of GBP1 in anti-tumor immunity has not yet been reported." (PMID 38758367, 2024). "Notably, TRIM31 (logFC = 1.14), ANXA1 (logFC = 1.05), GBP1 (logFC = 1.01), BIRC3 (logFC = 0.99), APOL1 (logFC = 0.97), IL18 (logFC = 0.94), ANXA2 (logFC = 0.89), BHLHE40 (logFC = 0.83), and EPHA2 (logFC = 0.75) exhibited significant upregulation in tumour tissues." (PMID 38254861, 2024). "Therefore, high GBP1 concentrations in the ascites may reflect local production by EOC cells, as evidenced by GBP1 detection by immunohistochemistry analyses in EOC samples and by Western blot analysis of tumor cell-enriched preparations from ascites." (PMID 32093058, 2020). "Together, these data demonstrate that GBP-1 promotes cell migration and invasion but not proliferation in GBM cells in vitro and promotes tumor formation in vivo." (PMID 39457021, 2024). "IFI30, GBP1 and GBP4 were upregulated 2-8-fold (p < 0.0001) in IFNγ positive tumors vs. IFNγ negative tumors in each of the six tumor types." (PMID 32265897, 2020). "Differential gene expression showed an enrichment of genes involved in T cell recruitment (CXCL9, CXLC10) and interferon-gamma activity (GBP1, STAT1) in the macrophage compartment of responding tumours, while non-responders were enriched in immunosuppressive markers (GPNMB, CCL18)." (PMID 38030622, 2023). "ITGAL, GBP1, GBP2 and ITGB2 were all upregulated in TLS positive tumors compared to TLS negative, but no changes could be observed in Tumor versus Normal and TLS positive versus Normal." (PMID 30082828, 2018). "Since phosphorylation in Ser 727 is functionally distinct from and independent of that in Tyr 701, the inability of the S727A mutant to abrogate cell death suggests that tumor suppression mediated by STAT1 does not require S727-dependent target genes, like GBP-1." (PMID 22264274, 2012).